ENSG00000269237 (novel transcript)
Gene: Protein-coding gene on chromosome 19 (21,405,159 to 21,491,266, forward strand). Ensembl gene ENSG00000269237.
Genetic constraint (gnomAD): Missense variants: 72 observed, 71.69 expected, observed/expected ratio (o/e) 1, 90% interval 0.83 to 1.22. Synonymous variants: 27 observed, 24.78 expected, observed/expected ratio (o/e) 1.09, 90% interval 0.8 to 1.5.